TLR7 (toll like receptor 7)
Diseases named in the same sentence as TLR7 in open-access papers (continued):
Sharing a sentence is not in itself a finding about the gene and the disease.
atherosclerosis (21 papers, 2008 to 2024). A disease characterized by the build-up of fatty material and calcium deposition in the arterial wall resulting in partial or complete occlusion of the arterial lumen. "In addition, TLR7-deficient mice were protected from diet-induced atherosclerosis due to a reduction of atherosclerotic lesion inflammatory cytokines and systemic levels of serum amyloid A." (PMID 31482095, 2019). "Therefore, TLR7 deficiency may attenuate atherosclerosis by altering the production of these pro- and anti-inflammatory cytokines." (PMID 28405010, 2017). "To test a direct participation of TLR7 in atherosclerosis, we crossbred TLR7-deficient (Tlr7−/−) mice with apolipoprotein E-deficient (Apoe−/−) mice and produced Apoe−/−Tlr7−/− and Apoe−/−Tlr7+/+ littermates, followed by feeding them an atherogenic diet to produce atherosclerosis." (PMID 28405010, 2017). "This discovery is consistent with prior studies showing the importance of TLR signaling in the progression of atherosclerosis and TLR7/9 signaling as a potential major contributor to the development of CD11c+ B cells." (PMID 38259450, 2023). "TLR7 can inhibit inflammation in atherosclerosis by secreting TNF-α and IL-10, so it is regarded as a prognosis marker in severe atherosclerosis patients." (PMID 38524701, 2023). "The expression level of TLR7 has been consistently very low in healthy human arterial specimens and higher in human atherosclerotic lesions, suggesting its involvement in atherosclerosis." (PMID 31482095, 2019). "To test a direct role of TLR7 in atherosclerosis, we generated Apoe−/−Tlr7−/− and Apoe−/−Tlr7+/+ littermate control mice." (PMID 28405010, 2017). "Nevertheless, results from this study support a pro-inflammatory role of TLR7 in atherogenic diet-induced atherosclerosis in Apoe−/− mice." (PMID 28405010, 2017). "Another study suggests that excessive expression of IFN-I through the activation of TLR7/9 signaling may induce accelerated atherosclerosis through the depletion or dysfunction of endothelial progenitor cells." (PMID 35059464, 2022). "The role of TLR7 has previously been investigated in atherosclerosis." (PMID 32708790, 2020). "In apoE*3-Leiden mouse restenosis model, TLR7/9 activation significantly led to femoral artery cuff intimal hyperplasia and accelerated atherosclerosis and blockade of TLR7/9 significantly reduced neointima formation, atherosclerosis, and macrophage cytokine production." (PMID 32850883, 2020). "Development of specific inhibitors of TLR7-sensing 2′-O-methylated RNAs may facilitate future therapeutic strategies to manage complex immunometabolic disorders such as obesity and atherosclerosis." (PMID 31482095, 2019). "However, human atherosclerotic lesions contained elevated levels of TLR721, suggesting an involvement of TLR7 in atherosclerosis." (PMID 28405010, 2017). "The role of TLR7 in atherosclerosis has also been controversial." (PMID 28405010, 2017). "It is possible that these virus affects atherosclerosis by activating TLR7." (PMID 28405010, 2017). "This study demonstrated a detrimental role of TLR7 in diet-induced atherosclerosis in Apoe−/− mice by increasing lesion inflammation (MHC-II), lesion pro-inflammatory cytokine expression (IL6), lesion protease expression (CatS, and MMP-9), and systemic inflammation (plasma SAA)." (PMID 28405010, 2017). "It is possible that TLR7 antagonists may have therapeutic potential in atherosclerosis and possibly other cardiovascular diseases." (PMID 28405010, 2017). "For example, anti-inflammatory monocyte adaptation by higher TLR7 agonist may hold potential value in the treatment of chronic inflammatory disease such as atherosclerosis." (PMID 27891130, 2016). "Interestingly, TLR7 has been shown to be protective in atherosclerosis." (PMID 32708790, 2020). "Therefore, the exact role of TLR7 in atherosclerosis remains uncertain and may depend on different experimental model systems." (PMID 28405010, 2017).
atherosclerosis (continued). "Such nucleotide(s) in atherosclerotic lesions may activate TLR7 and promote atherosclerosis." (PMID 28405010, 2017). "Up-regulated DEGs included known atherosclerosis genes such as the liver X receptor gene NR1H2, and NEXN, TRAF1, TLR7 and LGALS3BP, implicating tumor necrosis factor and toll-like receptor signaling and glycan-binding protein pathways." (PMID 37205656, 2023). "Our findings were partially substantiated by the reports that the antagonists of TLR7 and TLR9 reduced postinterventional remodeling by preventing neointima formation and accelerated atherosclerosis and chloroquine (a TLR9 inhibitor) induced atheroprotection." (PMID 26257462, 2015). "It is unclear if this can really explain the beneficial outcome of TLR7 signaling, since bone marrow chimeras for IFN-β exhibit reduced atherosclerosis, indicating that other downstream mechanisms could modulate the beneficial effect of TLR7." (PMID 30225265, 2018). "New developments in the basic understanding of the roles of TLR3, TLR6 and TLR7 from in vitro studies and pre-clinical models of disease may open up new avenues of TLR-targeted therapy for atherosclerosis." (PMID 23880853, 2013). "It is unclear if this can really explain the beneficial outcome of TLR7 signalling, since bone marrow chimeras for IFN-β exhibit reduced atherosclerosis, indicating that other downstream mechanisms could modulate the beneficial effect of TLR7." (PMID 23880853, 2013). "Endothelial cells, which do not express TLR7 or s-RNYs when stimulated with oxLDL/Tg,1 are not activated by extracellular s-RNYs, confining to immune cells the extracellular role of s-RNYs during atherosclerosis pathogenesis." (PMID 28055017, 2017). "Overexpression of IFN-I through the activation of TLR7/9 signal decreases the number and function of EPCs and increases atherosclerotic lesions in SLE patients, suggesting that targeted therapy of cGAS and RIG-I signal pathway may have a potential therapeutic effect on SLE atherosclerosis." (PMID 33262760, 2020). "However, the expression of TLR7 in atherosclerosis has not been reported before." (PMID 18673543, 2008). "Considering no direct evidence connecting CD38, PTPN11, NOTCH1, TLR7, and KAT2B with the pathogenesis of MMD, their roles in atherosclerosis may also provide a new perspective and direction for future research on the molecular targeted therapy of MMD." (PMID 36605987, 2022).
skin cancer (21 papers, 2009 to 2023). "Imiquimod, a TLR7 agonist, showed anti-tumor immunity in mice with skin tumors, even in Rag2−/− mice that are deficient in mature T and B cells." (PMID 35806328, 2022). "In addition, R-837 is known to inhibit cell growth especially in skin cancer, and we observed a higher sensitivity of TLR7-mutated cell lines to the CR42-24 compound." (PMID 29462934, 2018). "The TLR7 agonist imiquimod (R837) and the related resiquimod (R848) have been primarily tested in topical skin tumors due to systemic off-target effects." (PMID 36774352, 2023). "In fact, the synthetic TLR7/8 agonist IMQ is commonly used for the treatment of certain skin tumors." (PMID 36232698, 2022). "We tested the efficacy of the TLR7 agonist Imiquimod, previously used in skin cancer cutaneous metastatic breast cancer treatment, in reducing MDA-MB-231 cell proliferation." (PMID 34426608, 2021). "TLR7 agonists are the only toll-like receptor agonists approved for clinical treatment, although they are currently limited to topical use in various skin cancers." (PMID 33381518, 2020). "For example, the TLR7/8 ligands have been clinically applied in the treatment of skin cancers and actinic keratosis." (PMID 30774831, 2018). "The successful antitumor case of skin tumors that treated with imiquimod cream formulation showed that imiquimod acted as TLR7/8 agonist with antitumor properties." (PMID 27336891, 2016). "The efficacy of topical application of the TLR7/8 agonist imiquimod, the only TLR agonist approved by FDA for skin cancer treatment, has been linked to local increase of IFN-I production, recruitment of DC and induction of tumor-reactive CTL." (PMID 24400008, 2013). "Imiquimod is a TLR7 agonist with proven antitumor activity as a topical treatment for skin cancer." (PMID 31089331, 2019). "The TLR7/8 activator R848 is clinically approved for immunotherapy of skin tumors." (PMID 24371445, 2013). "Imidazoquinoline derivatives (IMDs) and related compounds function as synthetic agonists of Toll-like receptors 7 and 8 (TLR7/8) and one is FDA approved for topical antiviral and skin cancer treatments." (PMID 34058283, 2021). "Aldara cream is a topical skin cancer and keratosis treatment that contains IMQ, a toll-like receptor 7 agonist." (PMID 34572970, 2021). "Imiquimod, a selective TLR7 agonist via transcription factor NF-kB activation and production of inflammatory cytokines, such as type 1 IFN, is used as treatment for some skin tumors." (PMID 33342561, 2021). "Treatment of skin tumors (AK, superficial BCC, Bowen's disease and even lentigo maligna melanoma) with imiquimod (TLR7 and TLR9 agonist) activates the pDCs to produce type 1 IFN." (PMID 33342561, 2021). "Imiquimod is a topical TLR7 agonist, approved by the FDA for antiviral and skin cancer treatments." (PMID 36890302, 2023). "Increased CCL2 attracted pDCs to the skin tumor site, and recruited pDCs killed tumors directly by release or activation of cytotoxic effectors such as TNF-related apoptosis-inducing ligand (TRAIL), granzyme B (dependent on TLR7), and IFNAR signaling." (PMID 35806328, 2022). "Thus TLR3, TLR7/TLR8, and TLR9 activation are crucial therapeutic and adjuvant-based vaccine-oriented approaches to target skin cancers." (PMID 33510592, 2021). "It has been described that Imiquimod also directly induces cancer cell death, like other chemotherapeutic drugs, although the mechanism of Imiquimod-induced cell death is still unclear, particularly in skin cancer cells that do not express TLR7." (PMID 29422777, 2018). "The rejection of skin cancers by the local application of TLR-7 agonists occurs without direct evidence of adaptive immune responses." (PMID 19583830, 2009).
pneumonia (20 papers, 2015 to 2025). An acute, acute and chronic, or chronic inflammation focally or diffusely affecting the lung parenchyma, caused by an infection in one or both of the lungs (by bacteria, viruses, fungi, or mycoplasma.). "Our results further revealed that enhanced virus replication, virus-induced direct cytopathic effects, and neutrophil-mediated inflammation likely cause lung pathology and severe pneumonia in TLR7−/− mice compared to that observed in WT control mice." (PMID 40162785, 2025). "Some studies in the context of the COVID-19 pandemic have shown that tlr7 (rs179008) polymorphisms (in tlr7 gene) were significantly associated with an increased risk of pneumonia, increasing the risk of developing critical COVID-19 by 16 times for men with this mutation." (PMID 39861824, 2024). "Thus, the mechanisms underlying the hypersusceptibility of TLR7/9/13 triple KO mice to pneumonia are similar to those previously identified in MyD88-deficient mice, in which chemokine production and neutrophil recruitment to the lung were severely impaired." (PMID 32209688, 2020). "This suggests that Tlr7−/− mice were more susceptible to primary pneumonia." (PMID 28847850, 2017). "In Tlr7−/− mice, increased numbers of neutrophils may have initially led to improved bacterial clearance, but perhaps the congestion and tissue damage caused by neutrophils ultimately promoted the development of pneumonia." (PMID 28847850, 2017). "Here, using wild-type and TLR7-deficient (TLR7−/−) mice infected with mouse-adapted SARS-CoV-2 (MA-CoV-2), we examined the role of TLR7 in the lung antiviral and inflammatory response and severe pneumonia." (PMID 40162785, 2025). "Studies have shown that intestinal dysbiosis in influenza virus-infected mice causes severe damage to lung and intestinal tissues, whereas restoring intestinal microbiota can alleviate inflammation and pneumonia via the TLR7 signaling pathway." (PMID 39712501, 2024). "Taken together, the present study showed that early MJWQH treatment contributed to recovery from severe pneumonia due to its anti-inflammatory activity through regulating TLR7/MyD88/NF-κB signaling pathway." (PMID 26089947, 2015). "However, given the reduced inflammatory cytokine levels in TLR7−/−, it is unlikely that myeloid cell-mediated NF-κB/MAPK-induced inflammatory mediators caused severe pneumonia in TLR7−/− mice." (PMID 40162785, 2025). "In Baladi goats with pneumonia and healthy control group, PCR-DNA sequencing revealed SNPs linked to pneumonia susceptibility and resistance in immunological genes (SLC11A1, CD-14, CCL2, TLR1, TLR7, TLR8, TLR9, defensin, SP110, SPP1, BP1, A2M, ADORA3, CARD15, IRF3, and SCART1)." (PMID 40221769, 2025). "The immune genes’ mRNA levels in goats (SLC11A1, CD-14, CCL2, TLR1, TLR7, TLR8, TLR9, defensin, SP110, SPP1, BP1, A2M, ADORA3, CARD15, IRF3, and SCART1) varied between the healthy and infected goats with pneumonia." (PMID 40711280, 2025). "Using pneumonia virus of mice (PVM), a mouse pneumovirus that replicates the more severe forms of hRSV in children, we have previously shown that neonatal TLR7−/− mice develop severe bronchiolitis." (PMID 28539639, 2017). "In summary, we conclusively demonstrated that despite TLR7-induced robust lung inflammation, TLR7-induced IFN/ISG responses suppress lung virus replication and pathology and provide protection against SARS-CoV-2-induced fatal pneumonia." (PMID 40162785, 2025). "Through PCR-DNA sequencing in Baladi goats with and without pneumonia, SNPs linked to pneumonia susceptibility and resistance were discovered in the immunological (SLC11A1, CD-14, CCL2, TLR1, TLR7, TLR8, TLR9, defensin, SP110, SPP1, BP1, A2M, ADORA3, CARD15, IRF3, and SCART1) genes." (PMID 40711280, 2025). "The levels of immunological genes (SLC11A1, CD-14, CCL2, TLR1, TLR7, TLR8, TLR9, defensin, SP110, SPP1, BP1, A2M, ADORA3, CARD15, IRF3, and SCART1) vary in goats with and without pneumonia." (PMID 40221769, 2025).
pneumonia (continued). "Real-time PCR was conducted to quantify the expression levels of immunological markers (SLC11A1, CD-14, CCL2, TLR1, TLR7, TLR8, TLR9, β defensin, SP110, SPP1, BP1, A2M, ADORA3, CARD15, IRF3, and SCART1) in Baladi goats with and without pneumonia resistance." (PMID 36977224, 2023).
hepatocellular carcinoma (17 papers, 2011 to 2025). A malignant tumor that arises from hepatocytes. "The ability of HCV to suppress the expression of TLRs, including TLR3 and TLR7, could underlie its success in establishing a chronic infection that ultimately ends in cirrhosis and hepatocellular carcinoma." (PMID 24748896, 2014). "All mentioned studies can show the lack or decline of TLR7 expression has an important role in establishing a chronic infection that ultimately ends in cirrhosis and hepatocellular carcinoma." (PMID 37993939, 2023). "Antagonizing Toll-like receptor-7 lowers the growth rate of CSCs in hepatocellular carcinoma through TLR7-IKK-NF-kB-IL6 signaling pathway." (PMID 35505363, 2022). "We previously reported that TLR7 rs179009 minor allele G plays an important role in the progression of chronic HBV infection to the related liver cirrhosis and hepatocellular carcinoma in Chinese male adults." (PMID 33193416, 2020). "In summary, our mechanistic studies demonstrate that VD is involved in hepatocellular cancer possibly through TLR7 and TLR-related gene regulation." (PMID 27456065, 2016). "In a previous study, pDCs were shown to produce type I interferon in response to TLR7 mediated sensing of HCV infected hepatoma cells." (PMID 24788318, 2014). "Plasmacytoid dendritic cells are also the primary producers of type I IFNs in HCV infection and have been shown to respond to HCV infection in neighboring hepatocytes or hepatoma cells via TLR7." (PMID 24788318, 2014). "Moreover, combination therapy employing NK cells pre-activated with dendritic cells and the TLR7/8 agonist gardiquimod (GDQ) significantly suppresses the growth of human HepG2 liver carcinoma xenografts." (PMID 41488647, 2025). "TLR7 has been targeted as a potential therapeutic for hepatocellular carcinoma." (PMID 38476365, 2024). "Thus, the intratumoral delivery of HMGN1, the TLR7/8 agonist Resiquimod and checkpoint inhibitors cured established subcutaneous hepatomas and protected the mice against tumor rechallenge (see also TLR7/8)." (PMID 34025657, 2021). "In their study, TLR7 tended to gather in the perinuclei of hepatoma cells." (PMID 27588480, 2016). "In the field of hepatocellular carcinoma (HCC) therapy, clinical research on TLR7/8 agonists also warrants attention." (PMID 41488647, 2025). "In addition, human hepatoma cells expressed low levels of TLR7 mRNA following infection with HCV." (PMID 27135246, 2016). "In the realm of hepatocellular carcinoma (HCC) research, the inhibition of TLR7/9 by IRS—954 or chloroquine demonstrates potential efficacy." (PMID 40877572, 2025). "TLR3, TLR7, and TLR8 protein were undetectable in most hepatoma cell lines and A549 epithelial cells as measured by surface antibody staining." (PMID 34831243, 2021). "Next, we addressed expression levels of the endosomal RNA sensors TLR3, TLR7, and TLR8 as well as the TLR3 adaptor TIR domain-containing adaptor protein 1 (TICAM1 or TRIF) in hepatoma cell lines and primary hepatocytes." (PMID 34831243, 2021). "Microarray analysis demonstrates that TLR7 and TLR9 are overexpressed in human hepatocellular carcinomas (HCCs) compared with liver tissues from cirrhotic and viral hepatitis patients." (PMID 27456065, 2016). "TLR7 expression was up-regulated in human HCC tissues and hepatoma cell line." (PMID 27588480, 2016).